ADAMTS13 (ADAM metallopeptidase with thrombospondin type 1 motif 13)
Diseases named in the same sentence as ADAMTS13 in open-access papers (continued):
Sharing a sentence is not in itself a finding about the gene and the disease.
ischemia (9 papers, 2013 to 2025). A hypoperfusion of the BLOOD through an organ or tissue caused by a PATHOLOGIC CONSTRICTION or obstruction of its BLOOD VESSELS, or an absence of BLOOD CIRCULATION. "Deficiency of ADAMTS-13 results in microthrombi in the circulation resulting in ischemia and end-organ damage." (PMID 23537039, 2013). "Our findings suggested the involvement of proteins associated with thrombus formation (such as D-dimer and ADAMTS13), proteins associated with acute phase of ischemia (such as lipocalin-2, IP-10 and SAA), and angiogenic markers such as platelet derived growth factor (PDGF)-AA)." (PMID 33930055, 2021). "In PE, ADAMTS13 expression in the placental villous tissue is reduced, possibly emanating from placental ischemia, oxidative stress, and endotheliosis, implicating a role of ADAMTS13 protease in the pathogenesis of pregnancy-associated vascular remodeling." (PMID 40362344, 2025). "Low levels of ADAMTS13 activity result in microthrombi formation, which leads to end-organ ischemia and damage." (PMID 38758904, 2024). "Not surprisingly, with a decrease in VWF levels in all groups from baseline through basilar artery access and ischemia came a concurrent increase in ADAMTS13 levels to continually cleave the large multimeric VWF into a manageable size for further degradation." (PMID 39445200, 2024). "These indicate that ADAMTS13 protects the brain from ischemia-reperfusion injury predominantly through cleaving the endothelial cell-derived VWF." (PMID 31379722, 2019). "Both ADAMTS13−/− and wild-type control mice showed a significantly increased capillary density on the occluded side compared to the sham side, demonstrating effective angiogenic stimulation in response to ischemia." (PMID 41009700, 2025). "Insufficiency of ADAMTS-13 leads to the accumulation of very large vWF multimers, while the spontaneous formation of microthrombi in arterioles and capillaries is induced, followed by the development of ischemia." (PMID 35887770, 2022). "Apart from decreased blood flow, accumulation of inflammatory cells was observed in the brains of ADAMTS13−/−mice, suggesting that ADAMTS13 may protect the brain from ischemia by regulating VWF-dependent inflammation after reperfusion." (PMID 31379722, 2019). "Our findings suggest that ADAMTS13 does not play a critical role in ischemia-related angiogenesis and arteriogenesis under sterile conditions and may be relevant only in contexts involving acute and sufficiently strong thromboinflammatory stimuli." (PMID 41009700, 2025).
thrombotic disorders (9 papers, 2020 to 2025). "Secondary ADAMTS13 deficiency is considered to develop as a result of endothelial cell injury, and also this deficiency is known to be well associated with thrombotic disorders and severity or prognosis of primary diseases." (PMID 33712048, 2021). "ADAMTS13 deficiency has also been associated with other thrombotic disease processes." (PMID 39274365, 2024). "Thrombotic disorders commonly involved mutations in PROC (27%), PROS1 (12%), SERPINC1 (9%), ADAMTS13 (5%), and JAK2 (3%)." (PMID 40488813, 2025). "The penetrance of the thrombotic disease triggered by SARS-CoV-2 infection in heterozygous ADAMTS13 subjects is incomplete." (PMID 35746657, 2022). "The levels of decrease in ADAMTS13 seem to play important roles in the disease severity and thrombotic disorders." (PMID 33712048, 2021). "The ADAMTS13 protease regulates vWF activity by cleaving vWF multimers; therefore, an imbalance between vWF and ADAMTS13 may contribute to the development of thrombotic disorders." (PMID 41516301, 2025). "Evidence is emerging of the clinical effects of low ADAMTS13 activity in other disease areas outside of TTP, and here, we explore the wider impact of low ADAMTS13 activity on the vascular endothelium and the potential for recombinant ADAMTS13 therapy in other thrombotic disease states." (PMID 39274365, 2024). "However, cut-off values of ADAMTS13 activity that could predict the prognosis and the development of thrombotic disorders vary across different critical conditions." (PMID 33712048, 2021).
heart failure (8 papers, 2020 to 2025). Inability of the heart to pump blood at an adequate rate to meet tissue metabolic requirements. "This review evaluates the relationship of VWF and ADAMTS13 with cardiac disease, including cardiac failure, and associated pathophysiology." (PMID 34564132, 2021). "In a recent study, patients with newly diagnosed PAH had lower plasma levels of ADAMTS13 than healthy controls, as well as those with PH due to heart failure and chronic thromboembolic PH (CTEPH)." (PMID 37936223, 2023). "Given that the ADAMTS13‐TSP1 axis regulates CaMKII activation, which in turn is responsible for heart failure, we measured the expression of ADAMTS13 and TSP1 in mouse hearts." (PMID 36111515, 2022). "Decreased activity of ADAMTS13 with concomitant high VWF:Ag levels has also been demonstrated as an independent predictor of clinical events in patients with cardiac failure." (PMID 34564132, 2021). "There is evidence that in cardiomyocytes, the ADAMTS13‐thrombospondin 1 (TSP1) axis regulates CaMKII phosphorylation, which in turn is responsible for heart failure." (PMID 36111515, 2022).
thrombocytopenic purpura (8 papers, 2014 to 2025). Purpura associated with a reduction in circulating blood platelets which can result from a variety of factors. "The most severe deficiency (<10% of the reference values) of ADAMTS-13 occurs in thrombocytopenic purpura, a condition characterized by large VWF multimer sizes and, consequently, an increased risk of thrombosis." (PMID 35215805, 2022). "A deficiency of ADAMTS13 was related to thrombus formation and was subsequently noted in patients with thrombocytopenic purpura, who often suffered from TMA lesions in the kidney." (PMID 25372665, 2014). "Others go on to describe an imbalance between von Willebrand Factor and ADAMTS-13 axis mirroring pathology similar to thrombocytopenic purpura." (PMID 35355577, 2022). "Thrombotic Thrombocytopenic Purpura: ADAMTS13 (e.g., c.4143_4144insA)." (PMID 40822568, 2024). "Thrombocytopenic purpura (TTP) is a rare, potentially fatal pathology characterized by microangiopathic thrombotic syndrome and caused by an acute protease deficiency of von Willebrand factor, ADAMTS13." (PMID 35885465, 2022). "Thrombocytopenic purpura was ruled out with normal ADAMTS13 activity." (PMID 31245222, 2019). "Despite ADAMTS13 levels in AML were not as low as in thrombocytopenic purpura (TTP) patients, ADAMTS13 activity was lower than normal and played a role in disease progression due to increased VWF levels, so the risk of excessive platelet aggregation is higher." (PMID 40671161, 2025).
diabetic nephropathy (7 papers, 2016 to 2026). "The deterioration of renal function in diabetic nephropathy is associated with even lower ADAMTS-13 levels and a high VWF/ADAMTS-13 ratio." (PMID 40390002, 2025). "In several models, ADAMTS13 has been shown to exert protective anti-thrombotic and anti-inflammatory effects, for example, in diabetic nephropathy or myocardial pressure overload injury." (PMID 41009700, 2025). "Additionally, plasma ADAMTS-13 levels are decreased in diabetic nephropathy, potentially due to peripheral consumption for the cleavage of chronically increased VWF and an increase in circulating proteolytic enzymes (thrombin and plasmin) that cleave ADAMTS-13." (PMID 40390002, 2025).
endotoxemia (7 papers, 2011 to 2024). "In addition, mutation of the ADAMTS13 gene, marked cytokinemia, enhanced endotoxemia and/or the presence of protease inhibitors may be closely related to declining ADAMTS13: AC14,17." (PMID 30976044, 2019). "Alternatively, cytokinemia and endotoxemia are additional potential candidates for decreasing plasma ADAMTS13 : AC." (PMID 21994870, 2011). "To test this hypothesis, we investigated whether recombinant ADAMTS-13 improves the pathological course of endotoxemia in lipopolysaccharide (LPS)-treated mice." (PMID 37511541, 2023). "From these results as well as our own, marked cytokinemia and/or enhanced endotoxemia may be closely related to decreased ADAMTS13 : AC and the appearance of UL-VWFM." (PMID 21994870, 2011).
Obesity (7 papers, 2008 to 2024). Accumulation of substantial excess body fat. "Obesity and low enzyme A disintegrin and metalloproteinase with thrombospondin type-1 motif-13 (ADAMTS13) activity have been linked to poor coronavirus disease 2019 (COVID-19)." (PMID 38608066, 2024). "In the present study, we found that ADAMTS13 levels were positively associated with obesity and TC and that this association remained after adjusting for BMI and TC." (PMID 35392493, 2022). "ADAMTS13 levels have previously been reported to be associated with obesity (BMI) and blood lipid levels (cholesterol, TG, and HDL), while obesity is the strongest risk factor for the development of OSA." (PMID 35392493, 2022). "Obesity, black ethnicity (African Americans or Africans from the Caribbean), and female gender have all been shown to be associated with the development of anti-ADAMTS13 autoantibodies." (PMID 39205709, 2024). "Moreover, ADAMTS13 synthesis is significantly enhanced in mice with obesity and/or hypercholesterolemia compared with control animals, but the increase is primarily found in male mice, suggesting a sex-dependent regulatory mechanism." (PMID 35392493, 2022). "Lee observed a strong positive correlation between cholesterol and ADAMTS13 levels in wild-type mice, but their findings did not support a functional role for ADAMTS13 in obesity nor in associated angiogenesis or inflammation, at least in mice." (PMID 35392493, 2022). "In our study, we observed several highly case-specific variants in genes previously not directly linked to T2D and/or obesity (e.g., TMC8, PCDHA1, PLEKHA5, HBQ1, VAV3, and ADAMTS13)." (PMID 30126146, 2018).
pancreatitis (7 papers, 2012 to 2023). Inflammation of the pancreas. "Aside from the well-established role in hemostasis, the balance between ADAMTS13 and vWF has been linked to a variety of diseases, such as systemic inflammation, pancreatitis, and multiple sclerosis." (PMID 37226166, 2023).
sickle cell disease (7 papers, 2022 to 2025). Sickle cell anemias are chronic hemolytic diseases that may induce three types of acute accidents: severe anemia, severe bacterial infections, and ischemic vasoocclusive accidents (VOA) caused by sickle-shaped red blood cells obstructing small blood vessels and capillaries. "ADAMTS13 testing applications are increasing as its evaluation expands in different clinical scenarios, including trauma, septic shock, sickle cell anemia, and multiple hematological disorders." (PMID 40725629, 2025). "Recent studies have also reported that NET formation and ADAMTS13 deficiency similarly contribute to thrombosis and inflammation in other thrombo-inflammatory conditions, such as DIC and sickle cell disease, further supporting our findings." (PMID 40990987, 2025). "Sickle cell disease mice models appear to show a benefit of recombinant ADAMTS13; administering recombinant ADAMTS13 to these mice reduced hypoxia-reoxygenation induced haemolysis as well as systemic/local inflammation in lungs and kidneys." (PMID 39274365, 2024). "There is also an ongoing clinical trial investigating the benefit of recombinant ADAMTS13 therapy in sickle cell disease, which showed no safety signals or dose-limiting toxicities, such as bleeding events, in the Phase I placebo-controlled study." (PMID 39274365, 2024). "Comparable studies are limited, but there are 2 articles reporting TSP-1 to be inversely correlated with ADAMTS-13 in patients with acute coronary syndrome and adults with sickle cell disease but not in healthy controls." (PMID 37255854, 2023).
Von Willebrand disease (7 papers, 2012 to 2025). von Willebrand disease (VWD) is a hereditary bleeding disorder caused by a genetic anomaly leading to quantitative, structural or functional abnormalities of the Willebrand factor (von Willebrand factor; VWF). "Additionally, it is valuable to monitor this enzyme activity during von Willebrand Disease (VWD) type 2A since point mutations in the VWF A2-domain during this disease enhance VWF susceptibility to ADAMTS13-mediated proteolysis." (PMID 25992814, 2015). "In 4 out of 15 selected children with low ADAMTS-13 levels on admission, we found a remarkable reduction in the large and intermediate VWF multimers in the discharge blood samples, consistent with an acquired von Willebrand disease." (PMID 22563509, 2012).
Autoimmune (6 papers, 2014 to 2025). "Here we will discuss our current knowledge on processes implicated with the development of autoimmune disorders (ADs) and their relevance for the development of autoimmunity against ADAMTS13, considering both genetic and environmental factors." (PMID 34858410, 2021). "Autoimmune TTP is a life-threatening syndrome related to a severe deficiency of ADAMTS13 (<10%) secondary to anti-ADAMTS13 IgG antibodies." (PMID 28727752, 2017). "This review addresses the current knowledge on genetic factors associated with the development of iTTP and the interplay between the patient’s immune system and environmental factors in the induction of autoimmunity against ADAMTS13." (PMID 34858410, 2021). "The current knowledge allows us to propose a model for the role of infections and microbiota in the development of autoimmunity against ADAMTS13 in iTTP patients." (PMID 34858410, 2021). "It must be noted that detected IgG autoantibodies against ADAMTS13 may be confused from the assays with other non-ADAMTS13 antibodies present in patients suffering from another autoimmune condition." (PMID 39125707, 2024). "All patients were affected by autoimmune TTP (detectable anti-ADAMTS13 antibodies at least once in the patient’s history, before inclusion in the study); in all women except patient 11, severe ADAMTS13 deficiency (i.e., <10%) was detected in either acute or remission phase, out of pregnancy." (PMID 25431165, 2014).
Nephropathy (6 papers, 2015 to 2025). A nonspecific term referring to disease or damage of the kidneys. "The patient had low ADAMTS-13 activity (39%), hemoglobin cast nephropathy, microangiopathy, antiplatelet antibodies (GPIIb/IIIa, GPIb/IX, and GPIa/IIa), and “warm” IgG and C3d antibodies." (PMID 39156320, 2024). "However, the rise in ADAMTS13 antigen levels was not accompanied by a proportional increase in ADAMTS13 activity, since ADAMTS13 activity/ADAMTS13 Ag ratio was lower and VWF/ADAMTS13 activity ratio was higher in DM1 patients with nephropathy." (PMID 26770985, 2016). "Elevated levels of INF-γ, VWF, ADAMTS13 antigen, D-Dimer, and reduced ADAMTS13 activity/antigen ratio were observed in patients with nephropathy as compared to those without nephropathy (P = 0.001, P < 0.001, P < 0.001, P < 0.001, and P < 0.001, resp)." (PMID 26770985, 2016). "The association between high ADAMTS13 levels with mild and severe renal dysfunction, and with micro and macroalbuminuria may be explained by the presence of a compensatory mechanism, by which ADAMTS13 synthesis is increased due to the marked elevation in VWF plasma levels, as nephropathy progresses." (PMID 26168189, 2015). "Patients with CKD also presented elevated plasma levels of VWF, ADAMTS13 antigen, ADAMTS13 activity, D-Dimer and VWF/ADAMTS13 activity ratio, and a reduced ADAMTS13 activity/antigen ratio than those without nephropathy (P < 0.001, P < 0.001, P = 0.003, P < 0.001, P = 0.006, and P < 0.001, resp)." (PMID 26770985, 2016).
renal dysfunction (6 papers, 2015 to 2024). "Conversely, a low ADAMTS13 activity/ADAMTS13 Ag ratio was associated with mild and severe renal dysfunction, and with micro and macroalbuminuria, suggesting that the rise in ADAMTS13 Ag levels is not accompanied by a proportional increase in ADAMTS13 activity and VWF cleavage in these patients." (PMID 26168189, 2015). "On the other hand, ADAMTS-13 presented increased levels in patients with mild and severe renal dysfunction, which also correlates with an increase in D-dimer and Von Willebrand factor." (PMID 38892211, 2024). "ADAMTS13 activity/ADAMTS13 levels ratio was reduced in patients with mild (P=0.013) and severe (P=0.015) renal dysfunction as compared to the control group." (PMID 26168189, 2015). "ADAMTS13 levels were also increased in mild (P=0.029) and severe (P=0.002) renal dysfunction groups in comparison to the control group, while ADAMTS13 activity was increased only in the severe renal dysfunction group as compared to the control group (P=0.006)." (PMID 26168189, 2015). "Conversely, the ADAMTS13 activity/ADAMTS13 Ag ratio was reduced in patients with mild and severe renal dysfunction as compared to the control group (P = 0.013 and P = 0.015, respectively)." (PMID 26168189, 2015). "ADAMTS13 Ag levels were also elevated in mild and severe renal dysfunction groups of patients as compared to the control group (P = 0.029 and P = 0.002, respectively), while ADAMTS13 activity was elevated only in severe renal dysfunction group as compared to the control group (P = 0.006)." (PMID 26168189, 2015). "In agreement, this compensatory elevation in ADAMTS13 Ag levels and the increase in ADAMTS13 activity may be responsible for keeping VWF/ADAMTS13 Ag and VWF/ADAMTS13 activity ratios unchanged, as seen in patients with renal dysfunction." (PMID 26168189, 2015). "ADAMTS13 antigen and activity plasma levels were also elevated in DM1 patients with CKD as compared to those without renal dysfunction, which was also found in other studies." (PMID 26770985, 2016).
Thromboembolism (6 papers, 2017 to 2025). The formation of a blood clot inside a blood vessel that subsequently travels through the blood stream from the site where it formed to another location in the body, generally leading to vascular occlusion at the distant site. "Deficiency of the metalloproteinase ADAMTS13 has been linked to an increased risk of thromboembolism in patients with CRC, resulting in lower OS." (PMID 41152153, 2025). "A clinical study pointed out that ADAMTS13 can regulate the VWF thrombogenic activity, causing thromboembolism in AF." (PMID 34276770, 2021). "Several ADAMTS genes such as ADAMTS13 are involved in thromboembolic disease process." (PMID 32817637, 2020). "ROC was conducted for the peak D-dimer levels, ADAMTS13, and factor VIII levels for the development of thromboembolism, which revealed D-dimer as the best predictor with an area under the curve (AUC) of 0.836 (95% CI 0.729-0.913, p<0.0001)." (PMID 34476137, 2021). "Patients with symptomatic thromboembolism had higher peak D-dimer levels and lower factor VIII and ADAMTS13 activity." (PMID 34476137, 2021). "Reduced ADAMTS13 activity may result in an accumulation of ultra-large VWF on endothelial surface and heightened platelet adhesion and aggregation, promoting thromboembolism and metastasis." (PMID 29152610, 2017).
venous thromboembolism (6 papers, 2021 to 2025). Occlusion of the lumen of a vein by a thrombus that has migrated from a distal site via the blood stream. "The levels of serum MMP-9 were increased by SP but interestingly, the levels of ADAMTS13 (e.g., the decreased level is marker of venous thromboembolism, VTE) was decreased by SP injection in hACE2 mice, when compared with untreated hACE2 mice." (PMID 38077924, 2023). "Other studies have shown that the dysregulation of ADAMTS13 and VWF levels is involved in diseases such as chronic thromboembolic pulmonary hypertension and venous thromboembolism." (PMID 41585277, 2025). "In addition, a previous study has reported that patients with venous thromboembolism (VTE) have lower ADAMTS13:AC and higher VWF:Ag than those without VTE, indicating that the imbalance between ADAMTS13 enzyme and VWF substrate is associated with VTE." (PMID 35407443, 2022).